LINC01446 (long independently transcribed non-coding RNA 1446)
Synonyms: FLJ45974; GS1-179L18.1
Gene: Long non-coding RNA gene on chromosome 7 (53,655,504 to 53,811,952, reverse strand). Ensembl gene ENSG00000205628.
Diseases named in the same sentence as LINC01446 in open-access papers:
LINC01446 is named in the same sentence as 3 diseases in open-access papers, as found by Europe PMC text mining. Sharing a sentence is not in itself a finding about the gene and the disease. The quoted sentences say what the papers report.
glioblastoma (3 papers, 2020 to 2021). The most malignant astrocytic tumor (WHO grade IV). "LINC01446 functions as an oncogene and promotes GC and glioblastoma progression and indicates a poor prognosis, an effect similar to that predicted here." (PMID 34691143, 2021). "In glioblastoma, it is demonstrated that LINC01446 could promote cell proliferation and migration by competing with miRNAs and acting as ceRNAs14." (PMID 32651355, 2020).
tumor (1 paper, 2020). "To further evaluate the anticancer effect of si-LINC01446 and confirm our observation in GC cell lines, we interfered LINC01446 in primary GC cells that were isolated from tumor tissues from two GC patients." (PMID 32651355, 2020).
LINC01446 also shares sentences with these, for which no sentence is quoted: cancer (1 paper).